IL17A (interleukin 17A)
Diseases named in the same sentence as IL17A in open-access papers (continued):
Sharing a sentence is not in itself a finding about the gene and the disease.
inflammation (continued). "In conclusion, here we unravel a detailed signaling pathway, where ozone-induced neutrophilic airway inflammation and IL-17A production are mediated through the mitochondrial ROS-caspase-1-IL-1 cascade." (PMID 26739627, 2016). "Next, we used caspase-1 inhibitor to further investigate the role of caspase-1-IL-1 cascade in ozone-induced airway inflammation and in IL-17A+ γδT-cells generation." (PMID 26739627, 2016). "Il1r1−/− mice were protected from ozone-mediated airway inflammation, demonstrating that IL-1 pathway is necessary for IL-17A+ γδT-cells and neutrophilic airway inflammation." (PMID 26739627, 2016). "Nevertheless, further “in vivo” clinical study should be necessary to clarify the role of anticholinergic drugs in the control of mucus and inflammatory mediator secretion from bronchial epithelial cells during IL-17A mediated airway inflammation." (PMID 27298519, 2016). "Th17 cells, by virtue of secreting IL-17A, can recruit neutrophils to sites of vascular inflammation, and IL-23 helps sustain the population of Th17 cells." (PMID 27034824, 2016). "For example, while IL-22 can act synergistically with IL-17a in promoting pathological airway inflammation, both contribute to protective antimicrobial peptide expression in the skin." (PMID 26107738, 2015). "Frequent and concentrated sensitization induced exacerbation of lung inflammation immunologically and pathologically, and evoked intrapulmonary IL-17A and IL-10 production." (PMID 24928272, 2014). "It has been demonstrated that Th17 cells producing IL-17A are able to induce neutrophilic airway inflammation in mice and that this inflammation is GC insensitive." (PMID 23573194, 2013). "Th17 cells and IL17A can directly inhibit Th1 cells, and thereby suppress the development of intestinal inflammation." (PMID 24194940, 2013). "IL-22 has been shown to act synergistically with IL-17A to promote acute pathological airway inflammation." (PMID 23476100, 2013). "It has been demonstrated that IL-17A present in the lung, either produced by transgenic over-expression or induced by allergens, is able to induce lung inflammation, mucous metaplasia and airway hyperresponsiveness." (PMID 22848348, 2012). "Our study showed for the first time that IL-23p19 and IL-17RA signaling were necessary to trigger late pulmonary inflammation and fibrosis and confirmed by IL-17A neutralization that IL-17A is required for late disease." (PMID 21858022, 2011). "This epithelial injury triggers the release of alarmins IL-33 and TSLP, activates innate lymphoid cell types 2 (ILC2) and T cells, and promotes IL-5/IL-13-driven eosinophilic and interleukin-17A-mediated neutrophilic inflammation—resulting in mixed airway inflammation." (PMID 41450494, 2025). "Moreover, it is also linked to an increase in the number of tissues Th17 cells expressing CCR6, RORγt, and IL-17A in in vivo airway inflammation models." (PMID 41049431, 2025). "To define possible mechanisms underlying lung damage in DSS-treated TCRδ-/- mice, we analyzed the expression of genes encoding cytokines and chemokines known to contribute to predominately neutrophilic lung inflammation including Csf3, Cxcl2, Il17a, and the monocyte chemoattractant Ccl2." (PMID 37063825, 2023). "SNPs in PNPLA3, TNF-α, AGTR1, IL-17A, IL-1B, PTPRD, and GATAD2A cause liver inflammation." (PMID 36000237, 2022). "In vivo, treatment of Aspergillus-infected Il1r1–/– mice with anakinra increased the ratio of LC3-II/I and decreased p62, a ubiquitin-binding protein that is selectively degraded by autophagy; inhibited IL-6, IL-17A, IL-1β, and IL-1α production; increased IL-10; and ameliorated lung inflammation." (PMID 34847078, 2022). "This suggests that IL-17A-mediated inflammation (Th17 cells) may play a leading role in DSS-induced intestinal inflammation." (PMID 34407839, 2021).
inflammation (continued). "However, in line with increased neutrophil influx, we observed upregulation of il17a and tnfa, which are cytokines among others known to be induced during intestinal inflammation in mouse and humans." (PMID 34792120, 2021). "Moreover, IL-17A has a central role for the vascular infiltration of myeloid cells into the arterial wall in Angiotensin II-induced vascular inflammation." (PMID 31396305, 2019). "Prolonged (7 h) low-dose (0.7 ppm) ozone exposure resulted in neutrophilic airway inflammation, accompanied by an increased production of IL-1β, IL-18, IL-17A, Granulocyte-colony stimulating factor (G-CSF), INFγ-inducible protein 10 (IP-10) in BAL which were attenuated in IL-17(-/-) mice." (PMID 31354743, 2019). "Therefore, we examined the contribution of IL-17 to induction of OVA-induced airway inflammation in Il17a−/− mice sensitized “intranasally” with OVA in the presence of various sizes of chitin particles." (PMID 30082755, 2018). "In turn, these molecules, especially PGE2, further activate the CCR6+ memTh cells to produce more IL-17A, thereby creating a proinflammatory feedback loop that could drive the chronic synovial inflammation." (PMID 30236152, 2018). "Our results also demonstrate that IL-17A is essential for ozone-induced airway inflammation and that TCRγδ+ γδT-cells may contribute predominantly to IL-17A production." (PMID 26739627, 2016). "Our current study is not only in complete agreement with the findings showing that blocking IL-1 signaling effectively attenuates ozone-induced airway inflammation, but further provides a mechanistic link demonstrating that IL-17A-producing γδT-cells bridge IL-1 signaling and airway inflammation." (PMID 26739627, 2016). "We hypothesize that ozone-triggered inflammasome activation and interleukin (IL)-1 production regulate neutrophilic airway inflammation through IL-17A." (PMID 26739627, 2016). "In the present study, we hypothesize that ozone might activate the inflammasome to induce release of IL-1β and IL-18 in lung, and the latter in turn increases the production of IL-17A, ultimately leading to neutrophilic airway inflammation." (PMID 26739627, 2016). "Th17 lymphocytes, which produced IL-17A (also termed IL-17), IL-17F, and IL-22, represent a recently identified Th cell lineage that plays crucial roles by recruiting neutrophils and other cytokines in lung inflammations and diseases." (PMID 22615967, 2012). "To further understand the involvement of IL-17A, we investigated the role of IL-17A in the SEB augmented Ova induced lung inflammation and AHR using IL-17A deficient mice (IL-17A KO) as compared to age-matched wild type C57BL/6 mice using the same experimental protocol." (PMID 22848348, 2012). "Transgenic expression of IL-17A in the airway induced lung inflammation, mucous metaplasia, and airway fibrosis in mice and IL-17A may have direct effects on airway smooth muscle and may be responsible for allergen induced AHR." (PMID 22848348, 2012). "In addition, IL-17A and IL-17F stimulate keratinocytes and activate vascular inflammation." (PMID 32380665, 2020). "In this context, epistatic interactions between MMP1, IL10, and IL17A are biologically plausible, as excessive extracellular matrix degradation, impaired anti-inflammatory regulation, and enhanced Th17-driven responses may act synergistically to promote chronic periapical inflammation." (PMID 41614937, 2026). "Consistent with liver inflammation, the serum levels of pro-inflammatory proteins, including CCL2, CXCL9, IL-17a, IL-17f, and TNF receptor superfamily member 12a, were increased in HF-HC-fed mice." (PMID 41362710, 2025). "We also confirmed the induction of selected proteins uniquely induced by the combination of IL-17A/F and TNF-α in a murine model of airway inflammation." (PMID 36517803, 2022). "A gut-protective role for IL-17A has been described in an anti-CD3-induced, T cell-mediated acute intestinal inflammation in mice." (PMID 32676080, 2020).
inflammation (continued). "More detailed knowledge of the synovial inflammation associated with IL17A+ and CD21L+ expression should highlight additional targets and might offer the future prospect of selecting biological therapy based on the definition of these different types of joint synovial inflammation." (PMID 30114200, 2018). "Consistent with worsened renal dysfunction, Ang II infusion in the ApoEKO mice exhibited exacerbation of kidney inflammation with enhanced expression of TNF-α, TNFRSF1A, IL-1β, IL-6, and IL-17A." (PMID 26245758, 2015). "Our previous study of airway inflammation has demonstrated that the induction of IL-6 and CCL2 upon the interaction of basophils and bronchial epithelial cells under IL-17A stimulation was differentially regulated by ERK, JNK, p38 MAPK, and NF-κB pathways." (PMID 24782592, 2014). "The extent of increased IL-17A was correlated with the levels TGF-β in mouse lung after 16-week PM exposure, indicating that IL-17A and TGF-β might be cooperating in mediating pulmonary chronic inflammation." (PMID 35739565, 2022). "This is also a novel finding because a majority of the studies have only addressed the role of IL-17A in various models of chronic intestinal inflammation, particularly of the large intestines, not involving SAgs." (PMID 32676080, 2020). "Furthermore, SFA increased the number of lung macrophages, augmented HDM-induced neutrophilic airway inflammation and AHR, and increased the levels of IL-17A and MIP2 in HFD mice." (PMID 28365872, 2017). "Interestingly, during joint inflammation, overexpression of CLEC5A/MDL-1 recruits inflammatory cells and induces the production of IL-1, IL-6, IL-17A, and TNF, contributing to cartilage damage and bone erosion." (PMID 26086874, 2015). "Murine models of airway inflammation have shown that IL-22 can be pro-inflammatory (and thus pathological) in the presence of IL-17A but in the absence of IL-17A can be anti-inflammatory/tissue protective." (PMID 23555269, 2013). "According to these data, HDM-induced neutrophilic airway inflammation, AHR, and production of IL-17A and MIP2 cytokines in the lungs were augmented by an HFD, probably by increase in the number of lung macrophages, which might be related to the progression of airway inflammation." (PMID 28365872, 2017). "These macrophages together with IL-17A, SAA and innate NK cells are identified here as candidate persistence determinants and, we suggest, may represent specific targets for therapies directed towards the amelioration of chronic airway inflammation." (PMID 25405776, 2014). "However, another study showed that IL-22, but not IL-17A, could protect hepatocytes from acute liver inflammation." (PMID 32849528, 2020). "Interestingly, 5 of 8 ASD/SPAD children had chronic GI inflammation often complicated by dysbiosis and/or candida enteritis with evidence of positive reactivity to candida antigen when assessed by production of IFN-γ and IL-17A production at the time of flare up." (PMID 22226452, 2012).
bacterial infection (253 papers, 2009 to 2026). "Neutrophil recruitment to infected tissues is a hallmark of inflammation and bacterial infections and is partially driven by IL-17A (referred hereon as IL-17)." (PMID 41011451, 2025). "IL-17A production has been associated with recruiting neutrophils in response to bacterial infection." (PMID 38410509, 2024). "We have previously reported that induction of IL-17A in cattle infected with S. uberis appeared to be associated with neutrophil recruitment and clearance of bacterial infection." (PMID 34179160, 2021). "This demonstrates a protective role of IL-17A when expressed in response to bacterial infection, a role that is different from the pathogenic role when expressed by Th17 cells in autoimmune or chronic inflammatory diseases." (PMID 23378722, 2013). "Another possible mechanism by which type I IFN enhances host susceptibility to bacterial infection, relates to the observation that these cytokines stimulate the production of IL-27, a molecule that strongly suppresses IL-17A production." (PMID 21829705, 2011). "The ability of IL-17A to protect against bacterial infection and invasion has been linked with its ability to induce antimicrobial peptides and also to increased neutrophil microbicidal activity." (PMID 21060867, 2010). "Emerging evidence, beyond the well-characterized Candida risk, suggests that IL-17A blockade may predispose patients to serious bacterial infections." (PMID 40917923, 2025). "Our data support a model whereby impaired CD8 T cell production of IL-17A may contribute to the susceptibility to secondary bacterial infections in HIV infection." (PMID 39563891, 2024). "Aging, complication of bacterial infection, elevated disease activity, increased serum IL-17A level, positivity of anti-SRP antibody and steroid monotherapy were significantly correlated with development of PAH in IIM patients." (PMID 40138866, 2025). "The scoring system was named “BAIMS” arising from the initials of bacterial infection, age, IL-17A, MYOACT score, SRP and steroid monotherapy." (PMID 40138866, 2025). "We used qRT-PCR to quantify the expression of inflammatory genes commonly elevated in bacterial infections including the chemokine Cxcl1, cytokines (Il22, Il17a, and Il6), and the bactericidal antimicrobial peptide Reg3g." (PMID 41502946, 2025). "Other markers were also examined, such as IL-10, IL-17A, and M-CSF, which regulates the mobilization of neutrophils and macrophages/monocytes against bacterial infection." (PMID 39199203, 2024). "It has been proved that IL-17A plays a key role in the resistance of host animals against various bacterial infections." (PMID 38891619, 2024). "Reports indicate that both IL‐17F and IL‐17A are required for protection against bacterial infection." (PMID 38660962, 2024). "We recently showed the double-edged function of IL-17A; while protective against Spn colonization, IAV-induced IL-17A converted commensal Spn colonization into an invasive bacterial infection." (PMID 38060620, 2023). "In these studies, the authors detected decreased IL-17 production at early time points (1 day) after bacterial infection, because γδ T cells exhibited an early burst of IL-17A gene expression, which peaked at 8 h and declined by 24 h after bacterial infection." (PMID 37222516, 2023). "γδ T cells are specialized innate T cells that produce IL-17A and have important roles in protection against bacterial infection." (PMID 37222516, 2023). "IL-17A is an inflammatory cytokine that has a dual role in the context of immunity against bacterial infections." (PMID 36739443, 2023). "Depletion of IL-17A in preinfected mice with an IL-17A-neutralizing antibody abrogated Sp preinfection induced protection, suggesting that protection against secondary bacterial infection induced by prior Sp infection is dependent on IL-17A." (PMID 37222516, 2023).
bacterial infection (continued). "We next further investigated the role of IL-17A in protection against secondary bacterial infection following IAV infection by in vivo blockade of IL-17A." (PMID 37222516, 2023). "As a subset of T helper cells, Th17 cell signaling pathway leads to the secretion of proinflammatory cytokines such as IL-17A, which is important for host defense against fungal and extracellular bacterial infections." (PMID 35958876, 2022). "Although IL-17A can drive inflammation that damages the gut mucosa, IL-17A also play protective roles in limiting fungal and bacterial infection of the gut." (PMID 36289634, 2022). "Although mammalian IL-17A and IL-17F have many overlapping functions, they play different roles in host defense against bacterial infection." (PMID 34267744, 2021). "IL-17A and IL-22 are known to contribute to the epithelial barrier function against bacterial infection through inducing the production of AMPs, including β-defensins and S100 proteins." (PMID 33920301, 2021). "The results indicate that Pf_IL-17A/F1, 2 and 3 play different roles in promoting the inflammatory response and host defense against bacterial infection." (PMID 34267744, 2021). "Then, using mouse models, we demonstrated that TRM17 cells persist in the tissue after bacterial infection and can rapidly respond to inflammatory stimuli, such as IL-1β by producing IL-17A, which ultimately aggravates immune-mediated tissue injury." (PMID 33622974, 2021). "IL17A was predicted to be generally elevated in the sOP NP, undergoing an especially early activation upon bacterial infection." (PMID 32595639, 2020). "During bacterial infection, IL‐17A derived from activated lung γδT cells recruits neutrophils, induces mature granuloma formation, or induces Th17 immune responses to perform their defense functions." (PMID 31903715, 2020). "Similar to IL-17A and IL-17F, IL-17C also seems to mediate inflammatory processes and has been detected in lung and skin tissues after bacterial infection as well as in the colon of inflammatory bowel disease patients." (PMID 31221216, 2019). "This lineage CD4+ T cell produces unique cytokines IL-17A and IL-22, which play roles in inflammation pathogenesis and against extracellular fungi and bacterial infection." (PMID 31001353, 2019). "Our result aligns with that of a previous study, which demonstrated that gut epithelial barrier dysfunctions can be reversed by IL-17A neutralization in a neuro-psychoactive drug-induced bacterial infection model." (PMID 31727909, 2019). "Secretion of IL-17A into the nasal cavity recruited neutrophils that effectively removed the bacterial infection." (PMID 29375585, 2017). "IL-17A is a pro-inflammatory Th17 signature cytokine that controls bacterial infections by recruiting neutrophils." (PMID 26974441, 2016). "Conversely, in the spleen, the immune environment was shifted toward a mixed Th1/Th17 response, with increased IFNγ and IL-17A-producing CD4+ T cells, a hallmark of bacterial infection." (PMID 24945934, 2014). "IL-17A plays an important role in the recruitment and activation of neutrophils following bacterial infection." (PMID 24907978, 2014). "Th17 cell lineage produces not only IL-17A but also IL-22, both of which contribute to the controlling of extracellular bacterial infection by the induction of a powerful immune response." (PMID 24899787, 2014). "Similar observations were made in experimental Mycobacterium tuberculosis infection and in intraperitoneal infection with Escherichia coli, suggesting a more generalized role for IL-17A production by γδ T cells in immunity to bacterial infections." (PMID 22768117, 2012). "IL-17A and IL-17F are produced by Th17 cells and play major roles in neutrophil recruitment and protection against intracellular and extracellular bacterial infections." (PMID 21738762, 2011).